TTF1 (transcription termination factor 1)
Diseases named in the same sentence as TTF1 in open-access papers (continued):
Sharing a sentence is not in itself a finding about the gene and the disease.
mesothelioma (15 papers, 2006 to 2025). A usually malignant and aggressive neoplasm of the mesothelium which is often associated with exposure to asbestos. "TTF-1 is considered to be beneficial for distinguishing carcinomas with pulmonary and thyroid immunohistochemistry from other primary cancers, mesotheliomas and primary cutaneous Merkel cell carcinomas." (PMID 24932230, 2014). "Calretinin, WT-1 and D2-40 are recommended mesothelioma markers and CEA, Napsin-A and TTF-1 are recommended adenocarcinoma markers by IMIG (International Mesothelioma Interest Group)." (PMID 32731396, 2020). "The results of this study showed that CEA, CK7, TTF1, Calretinin and HBME1 are suitable criteria for differentiating between metastatic lung adenocarcinoma and mesothelioma, and can differentiate the mesothelioma and adenocarcinoma with high accuracy." (PMID 31528168, 2019). "Similarly, CEA, CK7, CK20, TTF1, and CDX2 are usually positive in adenocarcinoma cells, while WT-1, calretinin, D2-40, CK5/6, and cytokeratin are often positively expressed in mesothelioma cells." (PMID 37359022, 2023). "In our study, TTF1 was positive in 8 patients (61.5%) with adenocarcinoma, but negative in all patients (100%) with mesothelioma." (PMID 31528168, 2019). "In mesothelioma, positive markers, such as CK5/6, calretinin, WT‐1, HBME‐1, thrombomodulin, mesothelin and D2‐40, are commonly used, and negative markers such as TTF‐1, CEA, MOC31, BG8 and Ber‐EP4 are rarely expressed." (PMID 35950141, 2022). "In patients with mesothelioma, HBME1 and Calretinin were positive in 100% of patients (7 patients) and TTF1, CEA and CK7 were negative." (PMID 31528168, 2019). "Among the negative mesothelioma markers, MUC4, CEA, Claudin 4, TTF-1, and Napsin-A showed 100% sensitivity, p40 showed 95.4%, P63 showed 76.9%, and CK5/6 showed 69.2%." (PMID 29317712, 2018).
adenosquamous carcinoma (14 papers, 2012 to 2025). A carcinoma composed of malignant glandular cells and malignant squamous cells. "In two cases both TTF1 and p63 were expressed in different areas, thus these cases were classified as adenosquamous carcinoma." (PMID 39584166, 2024). "In adenosquamous carcinomas both p63 and TTF-1 can be present, but they have been evidenced in different areas of the tumor." (PMID 31935792, 2020). "Immunohistochemical positivity for CK7 and MUC5AC and negativity for TTF-1 and p63 aid in differentiating MEC from adenosquamous carcinoma and metastatic lesions." (PMID 41487813, 2025). "Our results confirmed that TTF-1 was very helpful in discriminating PMEC from primary pulmonary adenocarcinoma and adenosquamous carcinoma, including MEC-like carcinoma." (PMID 26575266, 2015). "TTF‐1 and napsin A are frequently positive in adenosquamous cell carcinoma but not in PMEC, thus assisting differentiation." (PMID 35747926, 2022). "The specimens of the other two EGFR-mutant cases (9%) were classified on biopsies as most likely adenosquamous carcinomas (ADSC), based on the co-existence of cells with mucin production, keratinization and ADC/SCC immunohistochemical markers (CK7+/TTF1+/CK5+/p40+)." (PMID 29899852, 2018). "TTF-1 and surfactant are commonly positive in adenosquamous carcinoma, while they are always negative in high-grade mucoepidermoid carcinoma of lung." (PMID 23114230, 2012).
medullary thyroid carcinoma (14 papers, 2012 to 2025). "This tumor showed positivity for cytokeratin AE1/AE3, carcinoembryonic antigen, synaptophysin, chromogranin, TTF-1, S-100, and calcitonin, indicating medullary thyroid carcinoma with a Ki-67 proliferation index of 10%." (PMID 39553134, 2024). "Histologic preparations should be reevaluated by IHC to guide the search for the primary tumor: TTF-1 (pulmonary or medullary thyroid carcinoma), CDX-2 (intestinal), PAX-8, histidine-decarboxylase (pancreatic), xenin (duodenal), gastrin (occult gastrinoma), and PP/glucagon (pancreatic)." (PMID 25038902, 2014). "Tenascin C, EGFR, E-cadherin, TTF-1-expression, and their correlations with RET mutation status were investigated in 30 patients with medullary thyroid carcinoma (MTC) (n = 26) or C-cell hyperplasia (n = 4)." (PMID 27409604, 2016). "Immunohistochemistry panels have been suggested for suspicious malignancies which include medullary carcinoma (calcitonin, thyroglobulin, CEA, and chromogranin), anaplastic carcinoma (pan-cytokeratin), and metastatic carcinoma (TTF-1)." (PMID 25688327, 2015). "TTF-1 staining has been useful to help distinguish these tumors as it is strongly and diffusely positive in medullary thyroid carcinoma, but usually negative (or only focally positive) in MDNC." (PMID 26491576, 2015). "The tumors were consistent with a neuroendocrine phenotype; showing strong immunoreactivity to chromogranin A and synaptophysin, but the immunohistochemical profile was inconsistent with medullary thyroid carcinoma in that the tumor was negative for calcitonin, CEA and TTF-1." (PMID 22369355, 2012). "Neoplastic cells showed strong immunoreactivity to chromogranin A and synaptophysin, but the immunohistochemical profile was inconsistent with medullary thyroid carcinoma in that the tumor was negative for calcitonin, carcinoembryonic antigen (CEA), and thyroid transcription factor-1 (TTF-1)." (PMID 22369355, 2012).
large cell carcinoma (12 papers, 2010 to 2025). A malignant epithelial neoplasm composed of large, atypical cells. "Eventually, a biopsy was performed of right-sided supraclavicular lymph node that showed metastasis of poorly differentiated large cell carcinoma with focal chromogranin and strong TTF-1 expression." (PMID 36135217, 2022). "In some cases, all results were negative after analysis using the primary antibodies ΔNP63 (P40), TTF-1, CK7 and 34βE12, and the cases should be diagnosed as large cell carcinoma." (PMID 25886585, 2015). "Previous studies have attempted to redefine LCC as a marker-negative or marker-null large cell carcinoma with the absence of TTF-1 and p40 based on IHC staining." (PMID 29246019, 2017). "Large cell carcinomas with rhabdoid morphology show expression of epithelial markers and vimentin like MRT, however in addition they also express CK7 and thyroid transcription factor-1 (TTF-1)." (PMID 25243090, 2014). "Interestingly, primary pulmonary TTF-1-negative non-mucinous AC as well as large-cell carcinomas expressed GI markers more often than TTF-1-positive non-mucinous AC in our material." (PMID 37349623, 2024). "Notably, the comparable frequency of KRAS G12C mutations in the “large cell carcinoma” histology group and lung adenocarcinoma supports the hypothesis that a substantial portion of large cell carcinomas are undifferentiated TTF1-negative adenocarcinomas." (PMID 40075878, 2025). "IHC markers such as p40 and TTF-1 are recommended for definitive histological diagnosis of SCC and AD when diagnosis is inconclusive based solely on the morphological features, in order to minimize the category NSCLC-not otherwise specified or large cell carcinoma." (PMID 27681076, 2016).
neuroendocrine carcinoma (12 papers, 2008 to 2026). A malignant neuroendocrine neoplasm composed of cells containing secretory granules that stain positive for NSE and chromogranin. "TTF-1 supports pulmonary origin and is frequently expressed in pulmonary adenocarcinoma and neuroendocrine carcinomas." (PMID 41010919, 2025). "TTF-1 is expressed by neuroendocrine and non-neuroendocrine carcinomas of the lung." (PMID 33504059, 2021). "All of the patients were diagnosed as neuroendocrine carcinoma according to the immunohistochemical staining (IHC) of specific markers, including chromogranin A (CgA), synaptophysin (Syn), CD56, and Thyroid transcription factor-1 (TTF-1)." (PMID 37920164, 2023). "TTF-1 expression, in fact, is not considered as specific for high-grade neuroendocrine carcinomas of lung origin." (PMID 33504059, 2021). "TTF-1 is positive in most cases of pulmonary small cell carcinoma, but also shows positive staining with many high-grade neuroendocrine carcinomas of non-pulmonary origin." (PMID 18197972, 2008). "In addition, the expression of PAX8 (clone SP348), WT1, Napsin A, or TTF1 (clone 8G7G3/1) is never or almost never present in TNBC (the latter outside of the context of neuroendocrine carcinoma)." (PMID 37306115, 2024). "The differential diagnosis of ONB and neuroendocrine carcinoma was considered as ONB is non-reactive with CK and TTF-1." (PMID 36452830, 2022).
anaplastic cancer (11 papers, 2011 to 2026). "The second missed mutation was from a bone metastasis sample of an undifferentiated carcinoma presumed to be of pulmonary origin, because it was TTF1-positive." (PMID 34898548, 2021). "Thyroglobulin and TTF-1 expression are lost in cases of anaplastic cancer." (PMID 35154933, 2022). "But only approximately 5.7 (2/35) to 18% (5/28) of anaplastic carcinomas are TTF-1 positive." (PMID 36329478, 2022).
colon carcinoma (11 papers, 2010 to 2026). "One case of TTF-1-positive metastatic lung cancer originating from colon cancer has already been reported." (PMID 29124480, 2017). "Importantly, TTF-1 positivity has been reported in a small percentage of breast and colon carcinomas." (PMID 20205775, 2010). "IHC stains such as TTF-1, CDX2, CK7, and CK20 help distinguish metastatic lung carcinoma from primary colonic cancer." (PMID 30961608, 2019).
pituicytoma (10 papers, 2011 to 2026). An extremely rare, WHO grade I, circumscribed and slow-growing tumor that arises from the neurohypophysis or infundibulum and described in adults. "Tumors positive for TTF-1 in the sellar region, such as pituicytoma, granular cell tumor, and spindle cell oncocytoma, originate from the posterior pituitary gland and are rare." (PMID 39353313, 2024). "Immunohistochemical staining showed that S-100 was strongly positive, GFAP was invisible or weakly positive, EMA was rarely positive, and TTF-1 positivity was helpful for the diagnosis of pituicytoma." (PMID 34210357, 2021). "Combined with our hospital and previous reports, the results of immunohistochemistry were analyzed as follows: It can be seen that TTF-1, S100 and vimentin were usually positive in pituicytomas, and the positive rates were 100%, 97.7% and 93.7% respectively." (PMID 33982223, 2021). "Because pituicytomas originate from pituitary cells, TTF-1 has been widely used in the diagnosis of pituicytomas in recent years." (PMID 34210357, 2021). "In general, all pituicytomas showed diffuse nuclear labeling for TTF-1 and positive expression of EMA, S100 and GFAP to varying degrees." (PMID 34210357, 2021). "ChG and pituicytomas share several similarities such as TTF1 expression and mTor pathway activation." (PMID 29915258, 2018). "However, TTF1 expression can also be found among low grade tumors as pituicytomas or spindle cell oncocytomas of the pituitary gland." (PMID 33876327, 2021). "The positive expression of TTF-1 in these 11 cases of SCO may facilitate further studies on the classification of these rare sellar tumors and may suggest that SCO and pituicytoma have a similar origin." (PMID 25777996, 2015). "The positivity of TTF-1 in our observation with these eight reported cases should lead to further research that could have implications for the classification of these rare sellar neoplasms and may indicate a similar origin of SCO and pituicytoma." (PMID 21320334, 2011).
Pleural effusion (10 papers, 2012 to 2026). The presence of an excessive amount of fluid in the pleural cavity. "TTF‐1 is the most frequently used immunohistochemical marker with a high specificity, both in tissue specimens and in pleural effusions." (PMID 28781870, 2017). "TTF-1 was partially positive in both differentiated and undifferentiated areas, which was compatible with the pleural effusion specimens." (PMID 25532447, 2014). "Interestingly, FAM83A staining was more pronounced in some LUAD pleural effusion samples that were weakly positive for TTF-1 or NapsinA." (PMID 38914812, 2024). "Cytological examination of pleural effusion showed that not all of them had papillary structures, nuclear sulcus, or pseudonuclear inclusion bodies, and not all of them had positive TG and TTF-1 expression on immunohistochemistry." (PMID 40502629, 2025). "The tumor cells were positive for CK7 and negative for CK20, TTF-1 and Napsin A, which was consistent with the result of the pleural effusion." (PMID 30634950, 2019). "The tumor cells in the pleural effusion were all negative for immunohistochemical markers (TTF-1 and Napsin A) and lung-specific oncogenic driver alterations (EGFR mutation and ALK translocation)." (PMID 30634950, 2019). "The expression pattern of FAM83A in the pleural effusion of LUAD patients was relatively consistent with that of TFF-1 and NapsinA, and even stronger in some specimens that were weakly positive or negative for TTF1/NapsinA." (PMID 38914812, 2024).
follicular thyroid carcinoma (9 papers, 2014 to 2025). "In both PTC and follicular thyroid carcinoma, TTF-1 expression has been reported in 95% or above, whereas approximately 7.5% is expressed in ATC." (PMID 39882267, 2024). "Metastatic follicular carcinoma of the thyroid shows TTF-1 expression, whereas metanephric adenoma shows tightly packed tubules lined by uniform cuboidal cells with occasional presence of papillary structures and diffuse positivity for WT1." (PMID 34514572, 2022). "TG and TTF-1 are reliable markers for thyroid follicular carcinoma and the final pathological diagnosis should be straightforward in the event of TTF-1 and TG immunopositivity." (PMID 28328844, 2017). "TTF-1 being specific to only thyroid and lung tissue and with no lung lesion visualized on imaging studies, diagnosis of follicular thyroid carcinoma with isolated liver metastasis at presentation was made." (PMID 27912795, 2016). "It morphologically resembles thyroid follicular carcinoma but does not express TTF-1 or TG." (PMID 24932236, 2014).
hepatocellular carcinoma (9 papers, 2014 to 2026). A malignant tumor that arises from hepatocytes. "The journal retracts the article titled, “TTF1, in the Form of Nanoparticles, Inhibits Angiogenesis, Cell Migration and Cell Invasion In Vitro and In Vivo in Human Hepatoma through STAT3 Regulation”, cited above." (PMID 41568994, 2026). "Another study also showed that the TTF-1 positive rates in hepatocellular carcinomas vary from 0% to 70% depending on the antibody manufacturer." (PMID 24860692, 2014). "Moreover, TTF-1 cytoplasmic staining is observed in normal hepatocytes and hepatocellular carcinomas." (PMID 40564811, 2025). "Furthermore, elevated expressions of RAGE, thyroid transcription factor 1 (TTF-1), glucose transporter 1 (GLUT-1), and SOX2 were suggested to be early events during the development of HCV (hepatitis C virus) associated hepatocellular carcinoma (HCC)." (PMID 34199060, 2021).
lung NETs (9 papers, 2011 to 2025). "Taken all together this data, it is possible to hypothesise that TTF-1 may be positively linked to increased angiogenesis, and associated with lower hypoxia and the absence of necrosis in lung neoplasms, potentially including lung NET." (PMID 37775725, 2024). "Available evidences suggest a specificity of this biomarker for the differential diagnosis of NET from different primary sites, but at the same time highlight that TTF-1 presents an extremely heterogeneous expression in lung NET." (PMID 37775725, 2024). "Overall, a positive staining for TTF-1 was detected in 49 (17.1%) of the included lung NET, with TTF‐1 positivity in 30 (13.0%) of the low Ki‐67 group of patients and in 19 (34.5%) cases of the high Ki‐67 group." (PMID 37775725, 2024). "This study highlights that TTF-1 positivity differs according to sex in lung NET, with a more common TTF-1 positive staining in female." (PMID 37775725, 2024). "Further studies with larger and independent patients’ populations are needed to confirm TTF-1 role as a gender-related biomarker for lung NET." (PMID 37775725, 2024). "However, the impact on OS was not statistically significant in the Cox regression analysis (p = 0.468, HR: 0.14, 95% CI 0.001–1414.981), confirming the controversial literature evidences about a possible prognostic role of TTF-1 for lung NET." (PMID 37775725, 2024). "Tumor expression of TTF-1 may also be utilized to aid in the diagnosis of lung NETs." (PMID 31511024, 2019). "TTF-1’s role as a prognostic biomarker for lung NET is still uncertain, and also in our analysis a not significant trend has been detected." (PMID 37775725, 2024). "Positivity for TTF‐1, a marker considered a characteristic of pulmonary neuroendocrine neoplasms, led only to a trend in prolongation of OS without reaching statistical significance." (PMID 27456539, 2016). "Negativity for the TTF-1 marker rules out the possibility of thyroid and primary neuroendocrine lung tumor as the primary site." (PMID 22069135, 2011). "Unfortunately, data about VEGF expression and TTF-1 in lung NET are lacking." (PMID 37775725, 2024). "In a retrospective study of 34 lung NET treated with peptide receptor radionuclide therapy with Lu-DOTATATE (Lu-PRRT), survival outcomes in terms of PFS were better in TTF-1 negative cases if compared to TTF-1 positive ones (26.3 vs. 7.2 months, respectively, p = 0.0009)." (PMID 37775725, 2024).
lung tumor (9 papers, 2012 to 2026). "This association of TTF1 positivity in the neoplastic cells with the existence of the lung tumor observed by imaging is absolutely necessary to determine, knowing that other tumors with extrapulmonary site show TTF1 positivity: thyroid and CNS (diencephalus) tumors." (PMID 39851953, 2025). "Negative staining for cytokeratin 7 (CK7), cytokeratin 20 (CK20), caudal-type homeobox transcription factor 2 (CDX2), and thyroid transcription factor 1 (TTF-1) helped exclude primary gastric, gastrointestinal, and pulmonary neoplasms." (PMID 41769517, 2026). "TTF-1 is a nuclear thyroid transcription factor expressed in normal lung and thyroid and is detected in 70% of human lung tumors." (PMID 39902337, 2024). "The thyroid transcription factor (TTF-1) is a well-known biomarker for lung neoplasms, above all for adenocarcinomas and for poorly differentiated lung neuroendocrine carcinomas." (PMID 36233825, 2022). "TTF-1 is a well-known biomarker for lung neoplasms, above all for adenocarcinomas." (PMID 37775725, 2024). "TTF-1 positivity in the lung tumor further supports a distinct lung primary." (PMID 28494807, 2017). "Only 3% of lung tumors were negative for SP-A, compared with 7 and 9% for Napsin A and TTF-1, respectively." (PMID 39902337, 2024). "In conclusion, the presence of high-grade fetal adenocarcinoma without TTF-1 expression, lack of beta-catenin mutation, and detection of 1q, +8q, and -5q by CGH in a biphasic lung tumour in adult patients favours the diagnosis of pulmonary carcinosarcoma." (PMID 23006472, 2012).